H2AP (H2A.P histone)
Synonyms: CXorf27; HYPM; HIP17
Tractability: No criterion of Open Targets' tractability assessment is met for any kind of drug.
Gene: Protein-coding gene on chromosome X (37,990,779 to 37,991,314, forward strand). Ensembl gene ENSG00000187516.
Gene Ontology:
Molecular function: protein binding; structural constituent of chromatin; protein heterodimerization activity
Biological process: heterochromatin formation
Cellular component: nucleosome
Homologues: Orthologues: chimpanzee H2AP (99% identical), mouse H2ap (48% identical), rat H2ap (48% identical).
Diseases named in the same sentence as H2AP in open-access papers:
H2AP is named in the same sentence as 1 disease in open-access papers, as found by Europe PMC text mining. Sharing a sentence is not in itself a finding about the gene and the disease.
H2AP shares sentences with these, for which no sentence is quoted: breast carcinoma (1 paper).